IL1B (interleukin 1 beta)
Diseases named in the same sentence as IL1B in open-access papers (continued):
Sharing a sentence is not in itself a finding about the gene and the disease.
infection (continued). "Given the critical role of IL-1β in immunity and inflammation during infection, we investigated the effect of EgCF on IL-1β secretion by macrophages." (PMID 37974225, 2023). "Overall, the mRNA levels of IL-1β peaked at 5 dpi in all four infection groups, with the IL-1β value in the rHLJ0504 group being the highest." (PMID 40303711, 2023). "By day 2 after infection, significant elevations in the levels of interleukin-1β (IL-1β), TNF-α, IL-6, IFN-γ, IFNα, IFNβ, CXCL1, CCL2, and CCL5 were detected in the airways of influenza virus–infected mice." (PMID 37683004, 2023). "IL‐1β is produced in the early stages of infection and is thought to be an important mediator of inflammation." (PMID 37644785, 2023). "After 14 days of infection, there were 257 genes with greater expression in nociceptor-ablated mice (e.g., Vegfa, IL1a, IL1b, and Tnf) compared to 219 genes with greater expression in control mice (e.g., Alox5, Car2, Ccl5, Elane, and Mmp8)." (PMID 37845223, 2023). "IL-1β secretes during the injury and infection of tissue and suggests the inflammatory states, which proof the different physiological effects." (PMID 38055394, 2023). "IL-1β is a pro-inflammatory cytokine (MW of ~17 kDa), required for host defense responses to infection and injury." (PMID 37366985, 2023). "Regarding the inflammatory cytokines, including G-CSF, GM-CSF, TNF-α, IL-1b, IL-6, and IL-17, the HD patients in the breakthrough infection group had higher TNF-α and IL-6 levels than those in the booster immunization group (p = 0.017 and 0.039, respectively)." (PMID 37515030, 2023). "After infection, the RNA level of IL-1β (p = 0.004) and TNF-α (p = 0.001) increased compared to controls, and these were significantly and dose-dependently inhibited (p < 0.05) by zingerone." (PMID 37626627, 2023). "In the present study, following infection with Salmonella Enteritidis, the levels of IL-1β, IFN-γ, TNF-α, and IL-6 rose dramatically, which is consistent with the findings of earlier research." (PMID 37990191, 2023). "In response to S. pneumoniae, we observed diminished IL-1β production in Ch25h−/− lung tissue isolated at 24 and 72 h post-infection." (PMID 36831236, 2023). "This difference decreases in NLRP3 knockout C57BL6 mice, suggesting NLRP3 and IL-1β protect against L. guyanensis-infection (de Carvalho RVH, Lima-Junior DS, 2019)." (PMID 37276232, 2023). "When IL-1β is released in response to infection or tissue damage, it activates other cytokines production, for instance, TNFα and IL-6." (PMID 38068877, 2023). "In the brain, IL-1β is required for learning and memory processes, but, when expressed at aberrant levels, it is involved in infection- and sterile inflammation-induced cognitive dysfunction." (PMID 37223102, 2023). "The infection decreased total white blood cells, lymphocytes, and the cytokine tumor necrosis factor-alpha level and increased cytokine interleukin-1-beta." (PMID 37627021, 2023). "The authors reported that neutrophils in which activation of the NLRC4 inflammasome occurred by transfection of bacterial flagellin or infection with Salmonella bacteria expressed IL-1β." (PMID 37047314, 2023). "TNF-α is produced in lymphocytes and has been reported to induce tumor necrosis or improve resistance to infection by foreign antigens by acting alone or in combination with IL-1β in an in vivo immune response." (PMID 36874224, 2023). "Infection with bacteria activates pro-inflammatory gene programs, such as expressing the IL-1β, IL-6, and tumor necrosis factor genes through transcription factors." (PMID 37958634, 2023). "The post-infection inflammatory cytokines (IL-1β and IL-8) and the COX-2 mediator were also reduced both in mRNA and protein expression levels." (PMID 37237883, 2023). "Historically, studies have posited that Coprococcus can modulate the production of cytokines IL-1β and IL-6, thereby orchestrating the inflammatory response during an infection." (PMID 37781358, 2023).
infection (continued). "Inflammatory factors like IL-6, IL-1β, and IFN-a or microorganisms biomarkers C. freundii, K. oxytoca, and E. cloacae need further research for indicating infection and constructing UTI diagnostic model of patients with CU." (PMID 36779185, 2023). "The culture supernatants from the infected and control BMDMs were analyzed 24 h post-infection for secreted levels of IL-1β." (PMID 37266012, 2023). "The protein level of IL-1β was also upregulated after ALKBH5 knockdown during infections by P. aeruginosa, C. diphtheriae, and the HSV-1 ICP34.5 mutant." (PMID 36625590, 2023). "By contrast, hvKp infection induced relatively low levels of Il1b and Il18 expression in these cells." (PMID 37457695, 2023). "Different molecules found during infection (PAMPs) or tissue damage (DAMPs) can trigger activation of the inflammasome and the processing and release of IL‐1β, a key mediator of the inflammatory response." (PMID 37031383, 2023). "Cytokine release analysis showed significantly elevated IL-2 responses in all seropositive individuals and elevated IL-1β responses in those recovered from symptomatic infection." (PMID 37885896, 2023). "Despite this decrease of inflammatory markers, at 72 h post-infection, a remarkable increase of cytokine expression (IL-17A, IL-6, IL-1β and IL-8) was detected." (PMID 37047702, 2023). "In a previous study, we found increased levels of IFN-γ, TNF-α, IL-17, and IL-1β in the spleens of μMT mice at two weeks post-infection." (PMID 37721965, 2023). "Monocyte-derived macrophages are a major source of IL-1β production during the immune response to pathogen infection." (PMID 37106440, 2023). "During infection, the lungs employ physical barriers and immune cells that release inflammatory cytokines like IL-6, IL-1β, and IL-18, initiating the inflammatory response." (PMID 37686825, 2023). "Firstly, DMI maintained the homeostasis of inflammation by reducing the level of proinflammatory (Il6 and Il1b) and anti-inflammatory (Il10) cytokines in vivo and in macrophages during infection." (PMID 36882813, 2023). "In the current study, we characterized the relative contributions of T3SS, the NLRP3 versus the NLRC4 inflammasomes, and GSDMD and GSDME to IL-1β release and pyroptosis in neutrophils versus macrophages following infection with P. aeruginosa." (PMID 37730693, 2023). "Peptidoglycan resistant to lysozyme strongly inhibited IL-1β production in response to infection in vitro and in vivo, suggesting that the S. aureus subverts IL-1β secretion by modifying its peptidoglycan from cell wall." (PMID 36761775, 2023). "Infection by T. rubrum was shown to stimulate the activation of nuclear factor kappa beta (NF-κB) and the production of IL-1β, IL-6, TNF-alpha and IL-10 by macrophages." (PMID 36838531, 2023). "IL-1β is a critical pro-inflammatory cytokine that is essential in response to infection and is thought to be induced mainly through the TLR/MyD88/NF-κB signaling pathway in monocytes/macrophages." (PMID 35928810, 2022). "Collectively, this work establishes a novel module involving IL-1β restricted IFN-β production during PA infection." (PMID 36190409, 2022). "IL1β is a potent proinflammatory cytokine essential for disease and infection responses and is an integral member of the IL-1 family, secreted by different cell types." (PMID 35624855, 2022). "STEC O113 ΔsubAB infection, however, resulted in much stronger expression of intracellular pro-IL-1β." (PMID 35345462, 2022). "The role of IL-1β throughout infection of the host with Mtb is complex with some evidence in support of a host protective role and other data supporting a role in increasing host susceptibility." (PMID 35237260, 2022). "Despite upregulation of M1-promoting cytokines (Ifng, Il1b) throughout the infection, inducible NO synthase (Nos2), the effector molecule of M1 polarization, exhibited none or negligible changes in expression." (PMID 35120185, 2022).
infection (continued). "Studies have also shown that WPM containing transition metals significantly increases the levels of several types of infection-related cytokines, such as IL-1β and IL-6, in the airway epithelium, resulting in airway wall collapse." (PMID 35837279, 2022). "We found that HAdV26 infection of human epithelial cells triggers the expression of pro-inflammatory cytokines, namely IL-6, IL-8, IL-1β, and TNF-α." (PMID 35458402, 2022). "Consistent with previous studies, infection with PA and the mRNA expression of inflammasome protein complex were related to IL-1β elevated in the PA group." (PMID 36190409, 2022). "Macrophage activation is an important strategy to prevent infection, and it is stimulated by cytokines such as interferon γ, IL-1β, and TNF-α or by certain bacterial extracellular components such as LPS and external chemicals." (PMID 35723329, 2022). "IL-1β was 29.00 ± 1.58 in fish coinfected with A. ocellatum and V. alginolyticus and 16.88 ± 0.75 in a single infection with A. ocellatum." (PMID 35573137, 2022). "In the priming step, expressions of NLRP3, pro-IL-1β, and pro-IL-18 are increased in response to stimuli, such as infection, injury, and ROS." (PMID 36289519, 2022). "Our data lead us to propose a model whereby PMNs transmigrate into the inflamed intestine, Caspase-1 is activated and IL-1β released to trigger epithelial cell death and shedding of infected cells to protect the epithelium from ongoing infection." (PMID 36191054, 2022). "Four dietary FPE concentrations were able to prevent the increase in splenic TNF-α, IL-8, and IL-1β expression levels elicited by infection." (PMID 34973140, 2022). "Transcripts encoding cytokines and chemokines such as IL-1β (interleukin-1β), IL-18, IL-6, IFN-γ, IL-10, CCL2 (C-C motif chemokine ligand 2), CCL4 and CCL7 were also up-regulated in the lungs during infection." (PMID 34965194, 2022). "By measuring the changes in the H/L ratio (an indicator of disease resistance) and three inflammatory factors (IFN-γ, IL-1β and IL-8) before and after ST infection, the resistance of the two chicken breeds to ST infection was determined." (PMID 36557693, 2022). "Since the myofibrils are disorganized after infection, we determined the effects of infection on the contractile apparatus CM lines in the absence or presence of IL-6 and IL-1β." (PMID 34669512, 2022). "Vaccinated pigs showed higher concentrations of IL-1β than the infection control group at the day of challenge and at 4 dpc (p < 0.05)." (PMID 36146761, 2022). "Upon infection, the inflammasome is activated, resulting in the production of IL-1β and IL-18, which recruits other immune cells to the site of infection." (PMID 35062292, 2022). "Propionibacterium acnes-mediated stimulation of THP-1 cells had a direct correlation with the expression of active caspase-1 and interleukin (IL)-1β in an infection-dependent manner." (PMID 35871079, 2022). "Day of euthanasia also significantly influenced all targets except Cox1; relative to placentae from mice infected at E6.5 (i.e., E15.5), transcripts for Ifnγ, Tnf, Il1β, Il10, and Cox2 in placentae from E8.5 infections (i.e., E16.5) were all elevated." (PMID 35312688, 2022). "Decreased levels of cytokine molecules (TNF-α, IL-1β) represent a reduction of cellular immunological function, which ultimately results in a high infection rate under external stressors." (PMID 35328551, 2022). "Whereas IL-1β is a potent pro-inflammatory cytokine that is crucial for host-defense responses to infection, few data suggest a direct inhibitory effect of IL-1β on viral replication." (PMID 35173184, 2022). "IL-1β induces the production of chemokines and proteases to attract other immune cells to the infection site." (PMID 35355981, 2022). "Exosomal GP63 of L. major parasites reportedly blocks ROS production by preventing PKC activation and degrades NLP3 inflammasome complex to prevent activation of IL-1β in both murine and human infection models." (PMID 35531875, 2022).
infection (continued). "Macrophages infected with ΔclsAB and ΔclsBC double mutants measured statistically reduced amounts of secreted IL-1β relative to those of the wild type, and the levels were identical to those elicited by the infection with ΔclsABC triple mutant bacteria." (PMID 35638781, 2022). "For example, the brain side of the gNVU showed IFN-γ, IL-6 and IL12-p70 as upregulated cytokines, while the vascular side showed IL-1β and IL-8 as upregulated cytokines in the context of infection by VEEV-TC83." (PMID 36560802, 2022). "Next, PBS- or Cl2MBP-liposome-treated WT mice were injected (i.v.)with BMDMs isolated from WT, Il-1β−/−, or Il-1α−/− mice prior to infection with R. typhi, R. rickettsii, or R. montanensis." (PMID 35130729, 2022). "One study has shown that mice infected with UPEC induced IL-1β release and that IL-1β was contributing to the severity of the infection." (PMID 35132157, 2022). "The transcriptional analysis of pulmonary inflammatory genes (including Il1b, Ifng, Il6, and Tnf) 3 days after infection with the different passages revealed a progressively increasing inflammatory response." (PMID 35023830, 2022). "We further tested the protein expression levels of pro-IL-1β and pro-IL-1α upon bacterial-infection of WT BMDMs and showed that pro-IL-1β levels were induced by all three Rickettsia spp." (PMID 35130729, 2022). "PhiMR003 did not change the number of inflammatory cells in the infiltrate during KYMR58 infection, even though IL-1β and IL-6 levels significantly decreased." (PMID 36123529, 2022). "On the other hand, TLR4 inhibition promoted a significant reduction of IL-1β after infection with L. corymbifera and M. circinelloides and TNF-α in response to M. circinelloides." (PMID 36311802, 2022). "The results of qRT-PCR showed that, in 5XFAD mice, the expression levels of TNF-α and IL-1β mRNA are elevated after infection with F. nucleatum." (PMID 35813949, 2022). "Recent studies have shown that renal inflammation can activate NLRP3 inflammatory vesicles, which trigger innate immune defenses via pro-inflammatory cytokines such as IL-1β in response to signals such as infection and metabolic dysregulation." (PMID 35873572, 2022). "The mRNA expression of il1-β and il-10 was found to increase in infected animals immediately after infection and were maintained along sampling times." (PMID 35163486, 2022). "Consistent with this view, some of the strain-specific characteristics of Lro in macrophage infections were reduced or abrogated by the reintroduction of fadB4: cytotoxicity, an increase in intracellular bacilli, and the IL-1β response." (PMID 36374090, 2022). "Deletion of the subAB gene enhanced production of IL-1β and IL-18 even more, as demonstrated in the experiment on subAB-deficient STEC O113: H21 (STEC O113 ΔsubAB) infection." (PMID 35345462, 2022). "Head kidney gene expression showed a down-regulation of il1β at 4 h and cd8α at 48 h following infection in fish fed TRP, while presenting a higher expression of tnfα at 24 h than that of the CTRL-fed fish." (PMID 36293344, 2022). "Inflammasomes are a molecular platform that are assembled to process pro-caspase 1 and subsequently promote secretion of interleukin (IL)-1β/IL-18 for proinflammatory responses induced upon infection." (PMID 35173184, 2022). "Cardiac toll-like receptors (TLRs) recognize general infection patterns and release proinflammatory cytokines such as interleukin-1β (IL-1β), IL-6, IL-18, TNF-α, and type I and type II interferons (IFNs)." (PMID 35479306, 2022). "The infection of A549 and SK-OV-3 with HAdV26 induced changes in the expression of the IL-6, IL-8, IL-1β, and TNF-α genes." (PMID 35458402, 2022). "Compared with the control, the expression levels of TNF-α (P < 0.01), IL-1β (P < 0.001) and IL-6 (P < 0.001) were significantly increased at 1 week after infection." (PMID 36171756, 2022).
infection (continued). "Mag-Pam2Cys_P48 treated moMΦ released higher levels of IL-1α, IL-1β, IL-1Ra, and IL-18 in response to infection with NH/P68 ASFV compared to 26544/OG10-infected and mock-infected controls." (PMID 36298767, 2022). "IL-1β, IL-8, and IL-18 are important cytokines regulating the inflammatory responses at the site of infection." (PMID 35587634, 2022). "Proinflammatory responses are then stablished, as judged by the release of cytokines (IFNɣ, IL-1β), which attract neutrophils and monocytes to the infection area." (PMID 36301982, 2022). "TNF-α and IL-1β, two potent pro-inflammatory cytokines, play an important role in the early stage of the inflammatory response to the infection of influenza virus." (PMID 35764970, 2022). "IL-1α and IL-1β, the pro-inflammatory cytokines that play a central role during infection were also significantly decreased in treated mice." (PMID 36430961, 2022). "This vascular architecture is essential for the control of glucose homeostasis, but also leads to β-cells being bathed in IL-1β during an infection." (PMID 34927076, 2022). "Interleukin (IL)-1β, a potent proinflammatory cytokine, plays a significant role in the host defense response to infection and injury." (PMID 36510222, 2022). "After PEDV-HBQY2016 strain infection, the expression levels of IL-1β, IL-6, MIP-1β, MCP-1, IL-8 and CXCL10 were significantly higher than those in in the control group." (PMID 36439802, 2022). "The only known report of inflammasome activation by Hantaan virus, a negative-sense RNA virus in the hantaviridae family, found activation of the NLRP3 inflammasome along with secretion of IL-1β upon infection of THP-1 cells." (PMID 36298668, 2022). "IL-1β is mainly produced by macrophages, monocytes and dendritic cells, which exerts a crucial role in the body’s immune response against infection." (PMID 35205991, 2022). "The BAL concentrations of IL-1β were also significantly higher in the Erdman relative to the CDC1551 group at Week 3 after infection, confirming higher macrophage activation upon infection with this strain." (PMID 35412961, 2022). "Infection with subAB-positive STEC O113:H21 (wild-type STEC O113:H21 [STEC O113 WT]) resulted in release of IL-1β and IL-18 from murine macrophage cell line J774.1 cells." (PMID 35345462, 2022). "NETs are recognized by macrophages as damage-associated molecular patterns (DAMPs) and are known to act as the initiator of IL-1β production and infection signals." (PMID 36142330, 2022). "This vascular architecture is essential for the control of glucose homeostasis, but also leads to β-cells being bathed in IL-1β during an infection or environmental insult." (PMID 35628520, 2022). "Adjuvanted vaccine groups showed lower levels of inflammatory cytokines (IL-6, IFN-γ, IL-1β) compared to the vaccine-only group or naïve mice after lethal infection." (PMID 36146461, 2022). "Our results, however, show that the expression of IL-1β mRNA was suppressed upon host cell infection by the wild-type strain of F. novicida and increased upon host cell infection with the ΔpyrC mutant strain." (PMID 36389167, 2022). "The inflammatory response of the body after infection initiates the NF-Kappa B signaling pathway, which induces the expression of cytokines such as IL-6, IL1β and TNF-a to eliminate pathogen invasion." (PMID 36091044, 2022). "The proinflammatory cytokines, TNFα and IL1β are key components of the innate immune response to infection." (PMID 35812870, 2022). "In brief, rMukHN494+495JS infection significantly upregulated the IL-1β level at 24 hpi and the IL-6 level at 12 and 24 hpi compared with rMukteswar infection in the spleen and thymus." (PMID 35711809, 2022). "Infection with YJH15 was also found to result in lower expression level of inflammatory cytokine IL-1β in blood and significantly decreased bacterial loads in heart, liver, spleen, lung, kidney and blood." (PMID 35281457, 2022).